GAPDHS (glyceraldehyde-3-phosphate dehydrogenase, spermatogenic)
Description:
Catalyzes the conversion of D-glyceraldehyde 3-phosphate (G3P) into 3-phospho-D-glyceroyl phosphate in glycolysis and the reverse reaction in gluconeogenesis (By similarity). May play an important role in regulating the switch between different pathways for energy production during spermiogenesis and in the spermatozoon. Required for sperm motility and male fertility (By similarity).
Synonyms: GAPDH-2; GAPD2; GAPDS; HSD-35; HEL-S-278
Tractability: Small molecule: a structure with a bound ligand is known; it has a high-quality binding pocket.
Gene: Protein-coding gene on chromosome 19 (35,533,455 to 35,545,319, forward strand). Ensembl gene ENSG00000105679.
Subcellular location: Cytoplasm
Subcellular location (Human Protein Atlas): Nucleoplasm; Principal piece; Centrosome
Pathways (Reactome):
Metabolism: Gluconeogenesis; Glycolysis
Metabolism of proteins: Association of TriC/CCT with target proteins during biosynthesis
Gene Ontology:
Molecular function: glyceraldehyde-3-phosphate dehydrogenase (NAD+) (phosphorylating) activity; protein binding; NAD binding; NADP binding; oxidoreductase activity, acting on the aldehyde or oxo group of donors, NAD or NADP as acceptor
Biological process: canonical glycolysis; flagellated sperm motility; gluconeogenesis; positive regulation of glycolytic process; glucose metabolic process; glycolytic process
Cellular component: nucleus; cytosol; cytoplasm
Genetic constraint (gnomAD): Loss-of-function variants: 31 observed, 34.69 expected, observed/expected ratio (o/e) 0.89, 90% interval 0.67 to 1.21. The synonymous counts are far from expectation, so gnomAD's model fits this gene poorly and the ratio says little. Missense variants: 452 observed, 513.16 expected, observed/expected ratio (o/e) 0.88, 90% interval 0.81 to 0.95. Synonymous variants: 150 observed, 207.21 expected, observed/expected ratio (o/e) 0.72, 90% interval 0.63 to 0.83.
Homologues: Orthologues: chimpanzee GAPDHS (99% identical), macaque GAPDHS (96% identical), dog GAPDHS (83% identical), guinea pig GAPDHS (82% identical), rabbit GAPDHS (82% identical), rat Gapdhs (82% identical), mouse Gapdhs (82% identical), pig GAPDHS (81% identical), zebrafish gapdhs (64% identical). Paralogues in human: GAPDH (56% identical).
Diseases named in the same sentence as GAPDHS in open-access papers:
GAPDHS is named in the same sentence as 21 diseases in open-access papers, as found by Europe PMC text mining. Sharing a sentence is not in itself a finding about the gene and the disease. The quoted sentences say what the papers report.
Infertility (5 papers, 2021 to 2025). "Although most studies on GAPDHS in humans focus on its role in infertility, emerging evidence suggests that this isoform also functions in carcinogenesis as a metabolic switch." (PMID 41009047, 2025). "Serum antibodies against GAPDHS were reported in higher concentrations in infertile men and women as compared to fertile individuals." (PMID 34576131, 2021). "Furthermore, the expression of GAPDHS, which was downregulated in sperm with Tmem225 deletion, resulted in reduced sperm motility and infertility in mice." (PMID 38246484, 2024). "MLX targets Gapdhs, and loss of GAPDHS results in infertility and nonmotile spermatozoa." (PMID 34669700, 2021).
melanoma (5 papers, 2018 to 2024). A malignant, usually aggressive tumor composed of atypical, neoplastic melanocytes. "In summary, our study demonstrates the essential role of GAPDHS in melanoma glycolysis and highlights its potential as a therapeutic target in melanoma management." (PMID 34249897, 2021). "For example, GAPDHS, an important gene in the glycolytic pathway, is highly expressed in melanoma and is a biomarker of poor prognosis." (PMID 34970420, 2021). "In conclusion, our study demonstrates the essential role of SOX10 and GAPDHS in melanoma glycolysis and highlights their potential as therapeutic targets in melanoma management." (PMID 34249897, 2021). "GAPDHS is an evolutionarily conserved essential enzyme in the glycolytic pathway, whose high expression in melanoma is a biomarker of poor prognosis." (PMID 34970420, 2021). "As expected, we eventually confirmed that GAPDHS could partially offset the inhibitory effect of shSOX10 on melanoma growth." (PMID 34249897, 2021). "This protein has unusual properties different from its somatic isoenzymes and could significantly influence metabolism and proliferation, and the presence of GAPDHS confers a number of unusual properties compared with those of GAPDH in melanoma." (PMID 34249897, 2021). "Second, GAPDHS is known to exhibit higher stability than GAPDH, which may cause the enzyme to hinder the translocation of GAPDHS into the nucleus to induce cell apoptosis that may play a role in the malignant phenotype of melanoma cells." (PMID 34249897, 2021). "As multiple lines of evidence suggest that GAPDHS is a key regulator of glycolysis in spermatogenic cells and facilitates glycolysis in melanoma cells, we then investigated whether the highly expressed GAPDHS regulates glucose metabolism in UM." (PMID 34249897, 2021). "Moreover, GAPDHS was identified as one of the top differentially expressed genes in human melanoma cells with NGLY1 knockdown, so it is also important to determine whether SOX10 cooperates with NGLY1 or other transcriptional regulators to promote melanomagenesis." (PMID 34249897, 2021). "A previous analysis showed that GAPDHS mRNA expression is enhanced in some melanoma cell lines compared with controls, and it has recently been correlated with an adverse clinical outcome in stage III–IV melanoma." (PMID 34249897, 2021). "Notably, we observed that GAPDHS mRNA was highly expressed in UM cells compared with the normal cell lines ARPE-19 and PIG1, which is consistent with a previous report that GAPDHS expression is significantly higher in human melanoma cell lines than in normal controls." (PMID 34249897, 2021).
asthenozoospermia (2 papers, 2023). "Furthermore, the GAPDHS content in the sperm of men with asthenozoospermia is lower than in the sperm of the control group." (PMID 36672976, 2023).
Azoospermia (2 papers, 2013 to 2020). Absence of any measurable level of sperm,whereby spermatozoa cannot be observed even after centrifugation of the semen pellet. "Abnormal GAPDHS expression led to non-obstructive azoospermia." (PMID 32787870, 2020). "In this work, we used the specimens from testicular biopsies of men with non-obstructive azoospermia who underwent TESE to investigate the expression of spermatogenesis-related genes MND1, SPATA22, GAPDHS and ACR." (PMID 23675907, 2013).
male infertility (2 papers, 2020 to 2023). The inability of the male to effect fertilization of an ovum after a specified period of unprotected intercourse. "Among these were well-studied protein biomarkers for male infertility such as IDH3A, GAPDHS, FH, and DLAT." (PMID 36509450, 2023). "Collectively, these results indicated that these proteins AKAP4, ODF1, ODF2, GAPDHS, SPESP1, and ACTRT2 were significantly down-regulated after heat treatment of scrotum, suggesting that these proteins may serve as the biomarkers for scrotal heat treatment-induced male infertility." (PMID 32787870, 2020).
Alzheimer disease (1 paper, 2022). A progressive, neurodegenerative disease characterized by loss of function and death of nerve cells in several areas of the brain leading to loss of cognitive function such as memory and language. "In addition, in the common carp liver, the KEGG pathway analysis showed that Alzheimer’s disease was related to genes INSR, GAPDHS, BAX, DHCR24, PPARG, ENO1, and VEGFA." (PMID 35741857, 2022).
Hypercholesterolemia (1 paper, 2013). An increased concentration of cholesterol in the blood. "Among the DEGs that were down-regulated in the hypertension plus hypercholesterolemia group were FOXN1, TNFRSF11B, and GAPDHS." (PMID 23874591, 2013).
lung carcinoma (1 paper, 2021). "In lung cancer tissue, high expression of GAPDHS, low expressions of ACSBG1, CYP4A11, mutated ACOX3, and old age predict a poor prognosis." (PMID 34970420, 2021). "Survival analysis of 43 differentially expressed MMRGs in lung cancer found that 3 differentially expressed MMRGs (GAPDHS, ACSBG1, and CYP4A11) had survival significance." (PMID 34970420, 2021). "High expression of GAPDHS, low expression of ACSBG1, low expression of CYP4A11, mutated ACOX3, and old age predict a poor prognosis of lung cancer." (PMID 34970420, 2021). "The advanced age, high expression of GAPDHS, low expressions of ACSBG1 and CYP4A11, and ACOX3 mutation were biomarkers of poor prognosis in lung cancers." (PMID 34970420, 2021). "The survival analysis of these 43 differentially expressed MMRGs found that the survival time was better in the low-expressed GAPDHS group than that in the high-expressed GAPDHS group of lung cancers." (PMID 34970420, 2021). "Multivariate Cox regression analysis of gender, age, stage, cancer type, GAPDHS, ACSBG1, and CYP4A11 found that older (>60 years) age, highly expressed GAPDHS, low expressed ACSBG1, and low expressed CYP4A11 were high-risk factors for lung cancer prognosis." (PMID 34970420, 2021). "Our study found the significantly high expression of GAPDHS, low expression of ACSBG1, and low expression of CYP4A11 in lung cancer tissues predicted poor prognosis for survival, whatever with single-factor and multifactor survival analytical strategies." (PMID 34970420, 2021). "Three survival-related differentially expressed MMRGs were found, including GAPDHS, ACSBG1, and CYP4A11, in lung cancer." (PMID 34970420, 2021).
uveal melanoma (1 paper, 2021). A melanoma derived from melanocytes of the uveal tract. "Here, we demonstrated that GAPDHS displays significantly higher expression in uveal melanoma (UM) than in normal controls." (PMID 34249897, 2021). "However, there is limited documentation of the functions of GAPDHS in tumors, and whether GAPDHS modulates glycolysis and tumorigenesis in uveal melanoma (UM) remains to be investigated." (PMID 34249897, 2021).
cancer (9 papers, 2018 to 2025). A tumor composed of atypical neoplastic, often pleomorphic cells that invade other tissues. "This analysis identified GAPDH (glyceraldehyde 3-phosphate dehydrogenase) and its paralog GAPDHS, which catalyze the sixth step (and a principal junction) of glycolysis, as strong modulators of cancer pH-dependent metabolism." (PMID 30065243, 2018). "Since our results clearly demonstrated that GAPDHS regulates aerobic glycolysis in UM, we further explored whether GAPDHS is critical for cancer proliferation." (PMID 34249897, 2021). "Similarly, we further explored whether SOX10 directly promotes GAPDHS expression and whether GAPDHS is critical for SOX10-regulated cancer proliferation in vivo." (PMID 34249897, 2021). "MYC, a well-known eccDNA-amplified driver gene which promotes cancer cell proliferation, immortalization and cross-resistance, was identified in the most cancer types (11 of 12) with the highest EGIS, followed by CCND1 (11 of 12), H3-5 (10 of 12), YWHAZ (10 of 12) and GAPDHS (10 of 12)." (PMID 40478912, 2025).
tumor (3 papers, 2020 to 2021). "In this study, we demonstrate that GAPDHS is significantly elevated in UM and functions in the control of glycolysis and promotes colony formation in vitro and tumor formation in vivo." (PMID 34249897, 2021). "Importantly, we also observed that tumor growth increased in the GAPDHS overexpression group compared with that in the SOX10 knockdown group, and the overexpression of GAPDHS partly rescued the impairment of tumor growth by shSOX10 in vivo." (PMID 34249897, 2021). "In addition, we assessed the role of GAPDHS in tumor formation with a colony-forming assay." (PMID 34249897, 2021).
infection (2 papers, 2015 to 2023). The state of being infected such as from the introduction of a foreign agent such as serum, vaccine, antigenic substance or organism. "Large scale proteomic studies have identified S-Nitrosylation of Arabidopsis GAPDHs during infection with avirulent Pst DC3000 and in response to treatment with nitric oxide." (PMID 25918875, 2015).
GAPDHS also shares sentences with these, for which no sentence is quoted: diabetes (2 papers); Arthritis (1); Hypertension (1); ischemia (1); lung adenocarcinoma (1); lung squamous cell carcinomas (1); Obesity (1); spondylitis (1); Stroke (1).